LDLRAD3 (low density lipoprotein receptor class A domain containing 3)
Description:
May influence APP processing, resulting in a decrease in sAPP-alpha production and increased amyloidogenic P3 peptide production. May regulate ITCH and NEDD4 E3 ligase activity and degradation. (Microbial infection) Acts as a receptor for Venezuelan equine encephalitis virus.
Synonyms: LRAD3
Tractability: Antibody: UniProt places it where antibodies can reach, with high confidence; UniProt predicts a signal peptide or a membrane-spanning region; its Gene Ontology location is reachable by antibodies, with medium confidence.
Gene: Protein-coding gene on chromosome 11 (35,943,981 to 36,232,138, forward strand). Ensembl gene ENSG00000179241.
Subcellular location: Cell membrane
Subcellular location (Human Protein Atlas): Cell Junctions
Gene Ontology:
Molecular function: protein binding; amyloid-beta binding
Biological process: receptor-mediated endocytosis; vesicle-mediated transport
Cellular component: plasma membrane; membrane
Genetic constraint (gnomAD): Loss-of-function variants: 22 observed, 30.42 expected, observed/expected ratio (o/e) 0.72, 90% interval 0.52 to 1.03. The synonymous counts are far from expectation, so gnomAD's model fits this gene poorly and the ratio says little. Missense variants: 404 observed, 457.76 expected, observed/expected ratio (o/e) 0.88, 90% interval 0.81 to 0.96. Synonymous variants: 149 observed, 193.39 expected, observed/expected ratio (o/e) 0.77, 90% interval 0.67 to 0.88.
Homologues: Orthologues: chimpanzee LDLRAD3 (100% identical), macaque LDLRAD3 (99% identical), pig LDLRAD3 (98% identical), mouse Ldlrad3 (96% identical), guinea pig LDLRAD3 (95% identical), rat Ldlrad3 (94% identical), rabbit LDLRAD3 (93% identical), dog LDLRAD3 (92% identical), tropical clawed frog ldlrad3 (73% identical).
Diseases named in the same sentence as LDLRAD3 in open-access papers:
LDLRAD3 is named in the same sentence as 27 diseases in open-access papers, as found by Europe PMC text mining. Sharing a sentence is not in itself a finding about the gene and the disease. The quoted sentences say what the papers report.
pancreatic cancer (20 papers, 2018 to 2024). "CircRNAs such as circ0001955 and circ-LDLRAD3 have shown promise as diagnostic and prognostic markers in cervical and pancreatic cancers, respectively." (PMID 39132504, 2024). "Circ-LDLRAD3 act as a diagnostic biomarker for pancreatic cancer, and its removal suppressed cancer progress Circ-LDLRAD3 was reported to be upregulated in the plasma of GC patients, suggesting that circ-LDLRAD3 may have a role in the development of GC8." (PMID 37587156, 2023). "For example, circ-LDLRAD3 could serve as a diagnostic biomarker of pancreatic cancer as its close correlation with venous and lymphatic invasion as well as metastasis." (PMID 33832516, 2021). "High expression of circ-LDLRAD3 is significantly correlated with venous or lymphatic infiltration and metastasis, and it may be used as a diagnostic biomarker for pancreatic cancer." (PMID 30064463, 2018). "Overexpression of circ-LDLRAD3 in pancreatic cancer is significantly correlated with venous and lymphatic infiltration as well as distant metastasis, and it is also a potential diagnostic marker for pancreatic cancer." (PMID 30064463, 2018). "Further analysis showed that high expression of circ-LDLRAD3 was a marker indicating a poor prognosis in patients with pancreatic cancer." (PMID 34439315, 2021). "It was found that the level of circ-LDLRAD3 was significantly increased in pancreatic cancer tissues and plasma compared to normal tissues or plasma." (PMID 34439315, 2021). "Circ-ASH2L, circBFAR, ciRS-7, hsa_circ_001653, CircFOXK2, circ-LDLRAD3, and circ_0030235 act as oncogenes in pancreatic cancer." (PMID 34183642, 2021). "A study has verified that circ-LDLRAD3 was up-regulated in plasma of pancreatic cancer patients compared with healthy controls, and the level of plasma circ-LDLRAD3 was strongly related to CA19-9, N classification, venous invasion, and lymphatic invasion." (PMID 33816529, 2021). "A combination of circ-LDLRAD3 with CA19-9 had a much higher diagnostic sensitivity and specificity for pancreatic cancer." (PMID 34439315, 2021). "For instance, circ-LDLRAD3 is upregulated in pancreatic cancer, and is disclosed to be a potential biomarker in disease diagnosis." (PMID 31948430, 2020). "The expression of circ-LDLRAD3 is increased in both pancreatic cancer tissues and plasma in patients with pancreatic cancer." (PMID 30111313, 2018). "Circ-LDLRAD3 is upregulated in both pancreatic cancer tissues and plasma obtained from patients with pancreatic cancer, and the AUC value, sensitivity and specificity when combined with CA19–9 was 0.87, 0.8033 and 0.9355, respectively." (PMID 30111313, 2018). "Similarly, circular RNA circ-LDLRAD3 is upregulated in pancreatic cancer, lung adenocarcinoma, gastric cancer and is significantly associated with venous invasion, lymphatic invasion, and metastasis in pancreatic cancer." (PMID 37251917, 2023). "T the circ‐LDLRAD3/miR‐137‐3p/PTN axis slows the progression of pancreatic cancer." (PMID 35588441, 2022). "In pancreatic cancer, circ-LDLRAD3 is an ideal marker of diagnosis and invasion capacity." (PMID 33710802, 2021). "In addition, several ncRNAs such as AFAP1-AS1, UCA1, HOTAIR, PVT1, MALAT-1, circ-ADAM9, BC008363, circ-LDLRAD3, circ-IARS, circ-PDE8A, circ_0030235, and circ_0001649 have been associated with prognosis of pancreatic cancer." (PMID 34439315, 2021). "Another circRNA circ-LDLRAD3 was shown to be overexpressed in pancreatic cancer tissues and cells." (PMID 34439315, 2021). "In addition, the high level of circ-LDLRAD3 was also significantly correlated with invasion and metastasis pancreatic cancer." (PMID 34439315, 2021). "Moreover, circ-LDLRAD3 was highly expressed in pancreatic cancer, while silencing circ-LDLRAD3 suppressed the progression of pancreatic cancer." (PMID 33425718, 2020). "Circular RNA circ‐LDLRAD3 is a biomarker in diagnosis of pancreatic cancer." (PMID 32185826, 2020).
pancreatic cancer (continued). "circ-LDLRAD3 is overexpressed in cells, tissues, and plasma samples of pancreatic cancer patients." (PMID 30064463, 2018). "circ-LDLRAD3 is another circRNA which could be used for the diagnosis of pancreatic cancer." (PMID 34439315, 2021). "Therefore, circ-PDE8A and Circ-IARS may be useful biomarkers for pancreatic cancer detection, circ-LDLRAD3 might be applied in the diagnosis and prognosis of pancreatic cancer." (PMID 33816529, 2021). "ROC analysis showed that circ-LDLRAD3 alone could efficiently diagnose pancreatic cancer." (PMID 34439315, 2021). "In a study on circ-LDLRAD3, the expression levels of circ-LDLRAD3 in pancreatic cancer and adjacent non-tumorous tissues, plasma samples from patients with pancreatic cancer and plasma samples from healthy subjects were measured." (PMID 34439315, 2021). "The role of LDLRAD3 in cancer has not been extensively studied, however, LDLRAD3 is overexpressed in several types of cancers including breast cancer, glioma, prostate adenocarcinoma, skin cutaneous melanoma, testicular germ cell tumor, and pancreatic cancer (TCGA, data not shown)." (PMID 37251917, 2023). "Furthermore, two independent studies identically discover that plasma circ-LDLRAD3 overexpression significantly correlates with pancreatic cancer, in which together with CA19-9, combinative test has 80.3% sensitivity and 93.6% specificity in early diagnosis of pancreatic cancer." (PMID 34434889, 2021).
colon cancer (1 paper, 2023). "As compared to control group, the expression of circ-NOL10, circ-LDLRAD3, circ-RHOT1, and CEA level in CRC, colon cancer, and rectum cancer patients was significantly upregulated (P ˂ 0.001, 0.001, 0.002), while circ-SMARCA5 was insignificantly upregulated (P = 0.233, 0.264, 0.280 respectively)." (PMID 37587156, 2023).
Crohn disease (1 paper, 2012). A gastrointestinal disorder characterized by chronic inflammation involving all layers of the intestinal wall, noncaseating granulomas affecting the intestinal wall and regional lymph nodes, and transmural fibrosis. "Interestingly, both LDLRAD3 and CACNA1B genes are involved in gastrointestinal diseases and polymorphisms in both these genes have been found to be associated with Crohn's disease making them both strong biological and positional candidates." (PMID 22396781, 2012).
lung squamous cell carcinoma (1 paper, 2023). "In a search of 10,565 cancer genomes from the TCGA database, a lung squamous cell carcinoma with the presence of LDLRAD3::SNCB fusion (TCGA-85-A50M-01A) was identified, among a total of 423 cases of lung squamous cell carcinoma." (PMID 37251917, 2023).
non-small cell lung carcinoma (1 paper, 2023). A group of at least three distinct histological types of lung cancer, including non-small cell squamous cell carcinoma, adenocarcinoma, and large cell carcinoma. "They found that circ-LDLRAD3 controls SLC1A5 via sponging miR-137 in non-small cell lung cancer cells, controlling tumor cell apoptosis, migration, and proliferation." (PMID 37161350, 2023).
polyp (1 paper, 2023). A usually exophytic mass attached to the underlying tissue by a broad base or a thin stalk. "For polyp patients, there were positive correlations between circ-RHOT1 and circ-NOL10, circ-LDLRAD3, CEA (P = 0.002, 0.039, 0.043 respectively)." (PMID 37587156, 2023).
retinal disease (1 paper, 2017). "Three genes had SNP associations to retinal disease: Ldlrad3, Fads2, and Fbln7." (PMID 29116131, 2017).
small cell lung carcinoma (1 paper, 2023). Small cell lung cancer (SCLC) is a highly aggressive malignant neoplasm, accounting for 10-15% of lung cancer cases, characterized byrapid growth, and early metastasis. "Circ-LDLRAD3 was an oncogenic factor in non-small cell lung cancer through miR-491-5P / mitogen-activated protein kinase kinase kinase 3 (MAP3K3) and miR-137 / lysine (K)-specific demethylase 1A (SLC1A5) pathways." (PMID 37587156, 2023).
virus infection (1 paper, 2024).
infection (7 papers, 2021 to 2025). The state of being infected such as from the introduction of a foreign agent such as serum, vaccine, antigenic substance or organism. "Overexpression of LDLRAD3 was associated with higher levels of infection, and cells expressing LDLRAD3 had a higher level of VEEV binding and internalization compared with knockout cells." (PMID 36647825, 2023). "Overexpression of LDLRAD3 significantly promoted the infection with pseudo-virions of VEEV, which is consistent with previous reports 14,15." (PMID 38245515, 2024). "Gene deletion of LDLRAD3 in mice was associated with 100% survival after infection with multiple VEEV strains, whereas congenic wild-type mice succumbed rapidly to infection." (PMID 36647825, 2023). "The high-resolution structural analysis of virus-receptor complexes (MXRA8-CHIKV, LDLRAD3-VEEV) along with detailed molecular analysis (SFV/EEEV-VLDLR) has enabled the generation of soluble decoy receptors that inhibit infection in cell culture and animals." (PMID 36647825, 2023). "Cell culture infection experiments with mouse and human cells and in vivo pathogenesis studies in mice defined LDLRAD3 as a cell-surface receptor for VEEV that is required for optimal infectivity and induction of encephalitis in mice." (PMID 34646020, 2021). "While detection of Ldlrad3 mRNA via fluorescent in situ hybridization (FISH) was observed in both iOSN and mOSN, it is likely that overall difference in levels of expression of Ldlrad3 underlie earlier infection of iOSN." (PMID 38233868, 2024). "D1 of LDLRAD3 is necessary and sufficient to support infection by VEEV1, but it remains unclear whether D2 also contributes to VEEV binding." (PMID 34646020, 2021). "LDLRAD3 is also important for infection of neurons, as intracranial inoculation of VEEV in LDLRAD3 KO mice showed limited infection in the brain and a significant reduction in mortality." (PMID 40005568, 2025). "Biolayer interferometry experiments established that domain 1 (D1) of LDLRAD3 (LDLRAD3(D1)) binds directly to VEEV, and anti-LDLRAD3 antibodies and LDLRAD3(D1)–Fc fusion proteins block VEEV attachment and infection of cells." (PMID 34646020, 2021). "Low-density lipoprotein receptor class A domain-containing 3 (LDLRAD3) was recently identified as an attachment and entry receptor for VEEV and shown to be essential for optimal infection in cell culture and pathogenesis in mice." (PMID 34646020, 2021). "While prophylactic administration of LDLRAD3-Fc fusion proteins suppresses peripheral infection and neuroinvasion, this does not suppress all replication within the brain." (PMID 38233868, 2024). "Whereas most mutant forms of LDLRAD3 promoted SINV–VEEV infection, several (including G33D, M36T, P44R and D57V) did not support infection even though the proteins were expressed on the cell surface at similar levels compared to the WT form of LDLRAD3." (PMID 34646020, 2021). "At the same time, overexpression of LDLRAD3, a known receptor for VEEV, did not increase rGETV-EGFP infection." (PMID 38245515, 2024).
cancer (5 papers, 2019 to 2023). A tumor composed of atypical neoplastic, often pleomorphic cells that invade other tissues. "Most of them has been confirmed to be associated with survival of different type of cancers; however, LDLRAD3 was rarely reported associated with cancer progression." (PMID 36817452, 2023). "Finally, we also confirmed LDLRAD3, which was rare reported in previous studies of cancers, was associated with worse survival of NSCLC patients." (PMID 36817452, 2023). "However, rare research reported the role of LDLRAD3 mRNA in cancers." (PMID 36817452, 2023). "Circ-SMARCA5, circ-NOL10, circ-LDLRAD3, and circ-RHOT1 were differentially expressed in patients with CRC as well as in non-cancer patients." (PMID 37587156, 2023). "This study provides new insights into the possible implication of circ-SMARCA5, circ-NOL10, circ-LDLRAD3, circ-RHOT1 in CRC progression, where they are expressed differentially in CRC patients as well as non-cancer patients (UC, polyp, and piles)." (PMID 37587156, 2023). "Due to the dynamic variation of the expressions of circ-SMARCA5, circ-NOL10, circ-LDLRAD3 and circ-RHOT in cancer, and non-cancer patients, these circRNAs might be prospective candidates for early diagnosis of CRC." (PMID 37587156, 2023).
tumor (5 papers, 2020 to 2023). "For instance, circ-LDLRAD3 was significantly upregulated in PAAD tissues and plasma, and a high level of circ-LDLRAD3 was positively associated with tumor venous invasion and lymphatic metastasis." (PMID 33842379, 2021). "Circ-SMARCA5 and circ-NOL10 may act as tumor suppressors, while circ-LDLRAD3 and circ-RHOT1 may be oncogenes." (PMID 37587156, 2023). "Here, we summarize ncRNAs with tumor-promoting functions: HOTAIR, HOTTIP, MALAT1, lncRNA H19, lncRNA PVT1, circ-RNA ciRS-7, circ-0030235, circ-RNA_100782, circ-LDLRAD3, circ-0007534, circRHOT1, circZMYM2, circ-IARS, circ-RNA PDE8A, miR-21, miR-155, miR-221/222, miR-196b, miR-10a." (PMID 32257946, 2020).
LDLRAD3 also shares sentences with these, for which no sentence is quoted: gastric cancer (2 papers); neurological disease (2); age-related macular degeneration (1); asthma (1); breast carcinoma (1); colorectal cancer (1); encephalitis (1); gastrointestinal disease (1); glioma (1); lung adenocarcinoma (1); lung carcinoma (1); prostate adenocarcinoma (1); rectum cancer (1); skin cutaneous melanoma (1); testicular germ cell tumor (1).